KIT (KIT proto-oncogene, receptor tyrosine kinase)
Diseases named in the same sentence as KIT in open-access papers (continued):
Sharing a sentence is not in itself a finding about the gene and the disease.
tumor (continued). "Previously, our group reported that silencing of the adaptor molecule SH3 Binding Protein 2 (SH3BP2) downregulated KIT and PDGFRA and microphthalmia-associated transcription factor (MITF) levels and reduced tumor growth." (PMID 36551682, 2022). "These exosomes increase the expression level of cyclin D1 and accelerate tumor cell proliferation by inducing the transfer of KIT protein that binds to the SCF in the tumor cells and leads to the PI3K/AKT signaling pathway." (PMID 35550636, 2022). "GIST are genetically driven neoplasms that are often treated with small molecule inhibitors targeting KIT and PDGFRα receptor tyrosine kinases." (PMID 36456699, 2022). "Overexpression of KIT prevented tumor-suppressive TGFβ signaling, while KIT deletion sensitized PDOs to TGFβ-mediated growth inhibition." (PMID 35842424, 2022). "This indicates that high KIT expression in NB tumors prevents apoptosis induction and stimulates mitosis, thus contributing to more aggressive tumor growth." (PMID 35887076, 2022). "As expected, nintedanib inhibited the KIT signalling pathway in KIT‐T670I/BaF3 tumour tissues in a dose‐dependent manner." (PMID 35194937, 2022). "We propose that KIT induces a pro-fibrotic tumor microenvironment by stimulating TGFβ expression, and protects the tumor cells from tumor-suppressive TGFβ signaling by inhibiting SMAD2 expression." (PMID 35842424, 2022). "KIT/PDGFRA WT GISTs are also among the tumor types that have been shown to harbor NTRK fusions with frequencies of 5–25%." (PMID 35681640, 2022). "A previous study had also demonstrated immunoreactivity for KIT in 12 out of 46 cases (26%) of feline soft tissue fibrosarcomas, with four of those cases demonstrating positive staining in greater than 80% of tumour cells." (PMID 36290122, 2022). "As evidenced by sequencing the tumor samples acquired after re-operation, we found two cases with the activation of proangiogenic pathways, including amplifications in KIT, FGFR, PDGFR, or KDR, and they exhibited the longest PFS." (PMID 36698900, 2022). "The CD73 marker was expressed only in tumor cells, whereas the mesenchymal stem cell receptor KIT was detected only in normal cells." (PMID 35884847, 2022). "Several sitravatinib targets, such as TAM receptors, MET, RET and KIT, are dysregulated in many types of cancer through overexpression or genetic alteration, and contribute to tumor development." (PMID 35767205, 2022). "In the present case, the presence of KIT exon 13 mutations was established based on NGS and morphological findings, i.e., abundant tumor cells, scarce myxoid stroma and strong diffuse expression of anti-CD117 antibody in tumor cells." (PMID 35488288, 2022). "We investigated 19,145 tumor RNA expression and molecular pathway activation profiles for 20 cancer types and detected relatively high levels of KIT expression in NB." (PMID 35887076, 2022). "To study how KIT expression regulates tumor cell-intrinsic TGFβ signaling, we used the various PDO cultures." (PMID 35842424, 2022). "According to the authors, some canine PC samples also exhibit positive c-KIT immunostaining in stromal cells, reflecting the importance of the stroma in maintaining the tumor microenvironment." (PMID 35681707, 2022). "Regorafenib, a multi-kinase inhibitor, inhibits several numbers of protein kinases implicated in tumour growth (KIT, RET, RAF-1, and BRAF p38 MAP kinase), metastasis (PDGFR- and FGFR1), and tumour angiogenesis (VEGFR-1, -2, and -3)." (PMID 36614133, 2022).
tumor (continued). "Alterations in KIT play an important role in tumor growth, proliferation and metastases in a variety of cancer." (PMID 34571863, 2021). "Imatinib-sensitive KIT mutant tumors contained greater frequencies of CD3 + and CD8 + T cells, but a lower percentage of CD4 + T cells and T regs compared to imatinib-resistant KIT mutant GIST tumor mouse models." (PMID 33402214, 2021). "Pazopanib is an oral, multi-targeted tyrosine kinase inhibitor, which has activity against VEGF-1–3, PDGFRα- β and KIT, resulting in tumor growth blockage and angiogenesis inhibition." (PMID 33842348, 2021). "Lastly, phosphorylation of other RTKs targeted by toceranib including KIT (33%) and Flt-3 (22%) was observed in a relatively small percentage of tumor samples." (PMID 34600548, 2021). "The c-KIT is a tyrosine kinase receptor, which is expressed on several types of cells, is thought to play a key role in tumor pathogenesis." (PMID 34439864, 2021). "Recent case reports evaluating genetically profiled tumours indicate that high SSTR2 receptor overexpression can be found in KIT mutant GIST as well as in dSDH wtGIST." (PMID 33443647, 2021). "The results revealed that most of the SRGs were differentially expressed and most of them were found increased in tumor tissues except for KIT, NGFR, SOX2 and KLF4 (sFigure 2A)." (PMID 34587919, 2021). "In contrast, KIT expression decreased in metastatic vs. primary SKMs, and the KIT mRNA level, in primary tumor, was inversely correlated with OS." (PMID 34769348, 2021). "In mice with GIST, the anti-KIT CAR T cells’ infusion resulted in a significant reduction in tumor growth." (PMID 34298737, 2021). "Levatinib is a MKI targeting VEGFR 1–3, fibroblast growth factor receptor 1–4, platelet derived growth factor receptor, RET and KIT with similar anti-tumor activity to sorafenib." (PMID 33923463, 2021). "Real time PCR was performed to provide an initial assessment of mRNA transcript expression of the RTKs PDGFRa, PDGFRb, VEGFR2, and KIT in primary UC tumor samples (N = 9) and established canine UC cell lines (N = 5)." (PMID 34600548, 2021). "Gene expression and DNA methylation data for KIT gene were extracted from the genome-wide transcriptomic and DNA methylation analysis, investigating 22 fresh frozen UM tumor samples from the same set." (PMID 34639089, 2021). "PDGFRA mutant tumor kinome profiles greatly differed from KIT/PDGFRA-WT tumors, with many kinases showing increased protein levels in PDGFRA mutant tumors relative to WT." (PMID 33320833, 2021). "At diagnosis, 80% have a mutation in KIT and 10% in PDGFRA, resulting in tyrosine kinase activation and tumor cell proliferation." (PMID 34552011, 2021). "In summary, we describe the anti-tumour growth properties of KITMAb, a monoclonal antibody with affinity for the dimerisation region of KIT." (PMID 33389076, 2021). "Transcript for PDGFRa, PDGFRb, VEGFR2, and KIT was detectable in all of the primary UC tumor samples and UC cell lines although this was present at varying degrees." (PMID 34600548, 2021). "The microscopic examination of the specimen showed spindle shaped tumor cells while immunohistochemistry showed CD117 (c-KIT) and DOG-1 positivity." (PMID 34274754, 2021). "As a result, targeting of the c-KIT pathway was considered to be an optimal approach for a tumor-specific treatment." (PMID 34829729, 2021). "In 85% of adults with GIST, gain-of-function mutation in KIT or, more rarely, PDGRF-α (PDGFRA) proto-oncogene causes tumor transformation at a critical early stage, leading to ligand-independent activation of KIT." (PMID 33507338, 2021). "While transcript for PDGFRα, PDGFRβ, VEGFR2 and KIT was detected in all tumor samples and UC cell lines, the pattern of expression was variable." (PMID 34600548, 2021). "Immunohistochemistry of the biopsy from the tumor showed a positive KIT protein, and the tumor was diagnosed as a gastric GIST." (PMID 32146688, 2020).
tumor (continued). "On the other hand, the OCSC marker c-KIT is highly expressed in hypoxic tumor microenvironments, which leads to β-catenin activation and high expression of ABC transporters that cause resistance to cisplatin/paclitaxel." (PMID 32512891, 2020). "Conversely, regorafenib, a novel oral MKI, blocks several protein kinases involved in the tumor angiogenesis (VEGFR-1, -2, and -3), tumor growth (KIT, RET, RAF-1, and BRAF), and metastasis (PDGFR-β, FGFR1) of cancer cells." (PMID 32466169, 2020). "Based on panel sequencing results with amplification of MET and KIT and tumor board decision, cabozantinib was initiated in a dose of 100 mg daily in the third relapse of the disease." (PMID 32758285, 2020). "Understanding the resistance to KIT inhibitors is therefore important to improve knowledge of tumor biology and the design of clinical research protocols with KIT inhibitors." (PMID 32344828, 2020). "75% of these tumor samples showed ≥1 (likely) pathogenic mutation, including targetable mutations (e.g. EGFR, BRAF, MET, ERBB2, KIT, PDGFRA)." (PMID 32264863, 2020). "The tissue expression of the KIT protein has also been investigated by immunohistochemistry (IHC) in various neoplasms, both in human and veterinary medicine (the latter particularly in pet dogs)." (PMID 33321993, 2020). "Although Garrido and Bastian suggested that CNAs and SNPs in hMM are mostly mutually exclusive, two different studies reported KIT amplification and coexisting SNPs in exons 11, 13, 17 and 18 in the same tumor." (PMID 33321993, 2020). "The family of tyrosine kinase receptors has been increasingly studied in humans for this type of neoplasm, especially the gene coding for the proto-oncogene KIT, and tyrosine kinase inhibitors are actually available as treatment." (PMID 33321993, 2020). "Ihle and colleagues reported that the downregulation of miR-221 and miR-222 induced apoptosis via the KIT/AKT pathway in GIST cells; the KIT/AKT pathway has effects on tumor progression, controlling cell proliferation and apoptosis." (PMID 33066449, 2020). "Plasma samples and matched tumor tissue were obtained simultaneously in cohort A from a total of 13 KIT- or PDGFRA-mutant GIST patients, and were subjected to amplicon-sequencing of 60 cancer-related genes." (PMID 32024476, 2020). "Of these tumours, SDH-deficient (characterized by the loss of SDHB) and quadruple WT GIST (KIT/PDGFRA/SDH/RAS-P WT) subgroups were reported to display a marked overexpression of FGF4, identifying a putative common therapeutic target for the first time." (PMID 33199729, 2020). "In EGIST, the degree of KIT and PDGFRA mutations varies on where the location of the tumor is, and it is suggested that omental EGIST is similar to gastric GIST." (PMID 32703220, 2020). "Immunohistochemistry revealed that the tumour was positive for KIT and CD34, and GIST was diagnosed." (PMID 32283516, 2020). "Downregulating KIT with a siRNA or HSP90AA1 inhibitors effectively reduced phosphorylated KIT and downstream signaling, which induced cell death and tumor shrinkage in IM-resistant GIST48 and GIST430 cells." (PMID 31363162, 2019). "The tumor consisted of a bundle of spindle cells that were strongly positive for KIT, CD-34, and discovered on gastrointestinal stromal tumor 1 (DOG1); the positive ratio of Ki-67 was 20%." (PMID 30943904, 2019). "Inhibition of SCF receptor c-KIT resulted in the attenuation of cancer stem cell enrichment and decreased amounts of tumor-initiating cells." (PMID 31336714, 2019). "Recent meta-analysis showed that high KIT expression in NBs correlates with worse prognoses independently from a tumor stage." (PMID 31681584, 2019).
tumor (continued). "In gastrointestinal stromal tumors, tumor EVs contained the oncogenic protein tyrosine kinase KIT and were shown to promote the invasion of the interstitial stroma, inducing a tumor phenotype in progenitor smooth muscle cells." (PMID 30872568, 2019). "The discovery of gain of function mutations on KIT and PDGFRA receptor genes led to a deep revolution in the knowledge of this tumor." (PMID 35582147, 2019). "Taken together, these data showed that IM combined with low-dose VPA reduced phospho-KIT and total KIT expression levels and had inhibitory effects on tumor growth in a GIST430 animal xenograft." (PMID 31363162, 2019). "Three molecular inhibitors of the Wnt signalling pathway have been reported to be tumour suppressors in various in vitro and in vivo GIST models harbouring a KIT mutation." (PMID 31552107, 2019). "Most KIT/PDGFRA mutated GISTs respond to the RTK inhibitor imatinib; however, treatment response is mainly depending on tumor genotype." (PMID 31124195, 2019). "Genetic analysis of the tumor was performed using a diagnostic biochip for the detection of somatic mutations in the BRAF, NRAS, KIT, GNAQ, GNA11, MAP2K1, and MAP2K2 genes, Sanger sequencing for searching germinal mutations in the CDKN2A gene." (PMID 30782194, 2019). "Of note, PDGFRA and KIT were expressed at relatively low levels in tumor tissue and higher in healthy kidney tissue." (PMID 30881919, 2019). "Taken together, KIT–9 mutant tumors tended to have CT imaging features indicative of more aggressive neoplasms." (PMID 31076599, 2019). "Lenvatinib inhibits similar tyrosine kinases to sorafenib and sunitinib; it works as an antiangiogenic (VEGFR-2 and PDGFR-α) drug and inhibits tumour growth (c-KIT and RET)." (PMID 31547602, 2019). "Genetic analysis of tumor tissue was performed using a diagnostic biochip (EIMB RAS, Russia) for the detection of most common somatic mutations in the BRAF, NRAS, KIT, GNAQ, GNA11, MAP2K1, and MAP2K2 genes." (PMID 30782194, 2019). "Our results suggest that HQP1351 is more effective in modulating the KIT signal transduction pathway and, potentially, more efficacious than ponatinib in tumor models in vivo, as well as in clinic." (PMID 31673329, 2019). "Upon immunohistochemical analysis, the tumor cells showed positivity for c-KIT and CD34 and very low positivity for Ki-67 and negativity for actin, desmin, HHF-35, S-100 protein, estrogen receptor (ER), and progesterone receptor (PgR)." (PMID 31410732, 2019). "Up-regulation of CXCR4 and KIT is associated with leukemic blasts and PCDH10 is a common tumor suppressor that is also epigenetically silenced in hematopoietic malignancies." (PMID 30575819, 2019). "On the other hand, except metabolism, the derived genes are also associated with distinct modes of tumor physiology in CRC, such as detoxification (GSTP1), metastasis (KIT), immunomodulation & stem cell renewal (CD44) and ER stress (CCT7)." (PMID 30809322, 2019). "Still, the abnormal expression of different RTKs, such as TrkA and KIT, can have a substantial impact on tumor formation and progression." (PMID 31681584, 2019). "Although baseline demographic features and KIT or PDGFRA exon mutation were similar between studies, there were differences in tumor burden and surgical intervention." (PMID 30693663, 2019).
tumor (continued). "Luckily, the discovery of gain-of-function mutations on KIT and PDGFRA receptor genes led to a deep revolution in the knowledge of this tumor and from a poor characterized entity, GIST became a paradigm of target therapy." (PMID 35582147, 2019). "The imatinib‐resistant GIST cell line GIST430/654 (KIT exon 11 delV560‐L576) with a secondary KIT mutation (KIT exon 13 V654) and similar kinetics to GIST882 to induce tumors was used as an imatinib‐resistant model for tumor growth in vivo." (PMID 29885053, 2018). "Lenvatinib is an oral, multitargeted TKI of VEGFR1-VEGFR3, RET, fibroblast growth factor receptors 1–4 (FGFR1-FGFR4), PDGFRα, and v-kit Hardy-Zuckerman 4 feline sarcoma viral oncogene homolog (KIT) signaling networks involved in tumor angiogenesis." (PMID 30619094, 2018). "There are, however, little data available for KIT mutational status in PDTC, although it is known that alterations in KIT transcripts increase with tumour progression from WDTC to PDTC." (PMID 29133385, 2018). "DNA aptamer based anti-human KIT sequences and mouse c-KIT aptamer targeted delivery of miR-26a protects mice from chemotherapy toxicity while suppressing tumour growth." (PMID 29653577, 2018). "Usually, these tumours arise from driver-mutations in KIT or PDGFRA genes and it is nowadays widely accepted that KIT protein expression is a hallmark of GIST." (PMID 29707131, 2018). "Our study confirmed the presence of 25% of mutation in HNMM, thus suggesting a route to study the pathophysiology of this tumor, with a focus on the MAPKs cascade and the inclusion of patients in clinical trials with KIT inhibitors." (PMID 29796159, 2018). "Consistently, CD44, OAS3, ISG15, STAT1, and WNT5A were significantly upregulated whereas KIT was significantly downregulated in tumor compared to normal in GSE13861." (PMID 30134903, 2018). "All the cases included were tested for KIT in more than one paraffin block (median 60% of all tumour; range 16%-100%), avoiding the potential heterogeneity of KIT expression in GIST samples." (PMID 29707131, 2018). "In the case of canine MM, tumor lines were generally unresponsive to KIT inhibitors such as Imatinib, which is consistent with the infrequency of KIT mutation." (PMID 29385676, 2018). "Immunohistochemical staining result was negative for β-human chorionic gonadotropin (HCG), but positive for placental alkaline phosphatase (PALP) and c-KIT (CD117) in the tumor cells." (PMID 29506496, 2018). "Immunohistochemical staining of the xenograft tumor sections indicated that the subcutaneous tumors of the miR-148b-3p-agomir-treated nude mice exhibited reduced signal for KIT compared to the control tumors." (PMID 29661252, 2018). "Altogether, our studies demonstrate frequent disruption of MAX tumour suppressive roles during early progression of KIT-mutant, PDGFRA-mutant and NF1-mutant GISTs." (PMID 28270683, 2017). "We also assessed which of the known cancer drivers, KIT, EGFR or MYC, had the closest association with tumor progression." (PMID 29088714, 2017). "Baseline patient and tumour profile characteristics showed a distinct profile (notably all were wild-type KIT/PDGFR) compared to that established for adults." (PMID 29110655, 2017). "This tumor also contained an activating KRAS alteration (p.G12D), a mutation that was also described in several KIT mutant GIST cases in a single report." (PMID 28768491, 2017). "To summarize, our findings suggest that crenolanib is a promising agent for the treatment of SM and other KIT D816-mutant neoplasms such as CBF AML – as a monotherapy as well as in combination regimens." (PMID 29137311, 2017). "Primary tumours showed a median c-KIT RQ of 0.7, while their corresponding metastases demonstrated lower transcript levels (median 0.1)." (PMID 29207991, 2017). "Sunitinib inhibits multiple tyrosine receptor kinases including PDGFR, VEGFR, and CD117 (c-KIT) to reduce tumor burden through decreased vascularization and enhanced cancer cell apoptosis." (PMID 28640223, 2017).